RNU6-629P (RNA, U6 small nuclear 629, pseudogene)
Gene: Small nuclear RNA gene on chromosome 2 (178,038,902 to 178,039,004, forward strand). Ensembl gene ENSG00000206788.
Homologues: Orthologues: chimpanzee U6 (98% identical), macaque U6 (91% identical), pig U6 (85% identical), rabbit U6 (81% identical), guinea pig U6 (72% identical). Paralogues in human: RNU6-1145P (92% identical), RNU6-15P (91% identical), RNU6-38P (91% identical), RNU6-1011P (90% identical), RNU6-16P (90% identical), RNU6-333P (90% identical), RNU6-393P (90% identical), RNU6-616P (90% identical), RNU6-1 (89% identical), RNU6-166P (89% identical), RNU6-2 (89% identical), RNU6-209P (89% identical), and 1288 more.